NUP133 (nucleoporin 133)
Description:
Involved in poly(A)+ RNA transport. Involved in nephrogenesis.
Synonyms: FLJ10814; GAMOS8; NPHS18; hNUP133
Tractability: Small molecule: it has a high-quality binding pocket. PROTAC: ubiquitination databases record sites on it; its protein half-life has been measured.
Gene: Protein-coding gene on chromosome 1 (229,440,259 to 229,508,356, reverse strand). Ensembl gene ENSG00000069248.
Subcellular location: Nucleus, nuclear pore complex; Chromosome, centromere, kinetochore
Subcellular location (Human Protein Atlas): Nuclear membrane
Pathways (Reactome):
Disease: Defective TPR may confer susceptibility towards thyroid papillary carcinoma (TPC); HCMV Early Events; HCMV Late Events; NEP/NS2 Interacts with the Cellular Export Machinery; NS1 Mediated Effects on Host Pathways; Nuclear import of Rev protein; Rev-mediated nuclear export of HIV RNA; SARS-CoV-2 activates/modulates innate and adaptive immune responses; Transport of Ribonucleoproteins into the Host Nucleus; Viral Messenger RNA Synthesis; Vpr-mediated nuclear import of PICs
Cell Cycle: Amplification of signal from unattached kinetochores via a MAD2 inhibitory signal; EML4 and NUDC in mitotic spindle formation; Mitotic Prometaphase; Nuclear Pore Complex (NPC) Disassembly; Postmitotic nuclear pore complex (NPC) reformation; Resolution of Sister Chromatid Cohesion; Separation of Sister Chromatids
Metabolism of RNA: Transport of Mature mRNA Derived from an Intronless Transcript; Transport of Mature mRNA derived from an Intron-Containing Transcript; Transport of the SLBP Dependant Mature mRNA; Transport of the SLBP independent Mature mRNA; snRNP Assembly; tRNA processing in the nucleus
Metabolism of proteins: SUMOylation of DNA damage response and repair proteins; SUMOylation of DNA replication proteins; SUMOylation of RNA binding proteins; SUMOylation of SUMOylation proteins; SUMOylation of chromatin organization proteins; SUMOylation of ubiquitinylation proteins
Metabolism: IP3 and IP4 transport between cytosol and nucleus; IP6 and IP7 transport between cytosol and nucleus; IPs transport between nucleus and cytosol; Regulation of Glucokinase by Glucokinase Regulatory Protein
Cellular responses to stimuli: Regulation of HSF1-mediated heat shock response
Immune System: ISG15 antiviral mechanism
Signal Transduction: RHO GTPases Activate Formins
Gene Ontology:
Molecular function: protein binding; structural constituent of nuclear pore
Biological process: mRNA export from nucleus; nephron development; nuclear pore organization; nucleocytoplasmic transport; poly(A)+ mRNA export from nucleus; protein import into nucleus; transcription-dependent tethering of RNA polymerase II gene DNA at nuclear periphery; animal organ development; system development
Cellular component: kinetochore; membrane; nuclear envelope; nuclear membrane; nuclear pore; nuclear pore outer ring; cytosol
Genetic constraint (gnomAD): Loss-of-function variants: 40 observed, 91.36 expected, observed/expected ratio (o/e) 0.44, 90% interval 0.34 to 0.57. The upper end of that interval is the gene's LOEUF score, 0.57, which puts it in group 2 of 6, group 1 being the genes least tolerant of losing a copy. Missense variants: 988 observed, 1,084.5 expected, observed/expected ratio (o/e) 0.91, 90% interval 0.86 to 0.96. Synonymous variants: 428 observed, 407.27 expected, observed/expected ratio (o/e) 1.05, 90% interval 0.97 to 1.14.
Homologues: Orthologues: chimpanzee NUP133 (99% identical), macaque NUP133 (98% identical), dog NUP133 (91% identical), rabbit NUP133 (91% identical), pig NUP133 (90% identical), guinea pig NUP133 (85% identical), mouse Nup133 (83% identical), rat Nup133 (83% identical), tropical clawed frog nup133 (65% identical), zebrafish nup133 (58% identical), Drosophila melanogaster Nup133 (28% identical), Caenorhabditis elegans npp-15 (20% identical).
Diseases named in the same sentence as NUP133 in open-access papers:
NUP133 is named in the same sentence as 18 diseases in open-access papers, as found by Europe PMC text mining. Sharing a sentence is not in itself a finding about the gene and the disease. The quoted sentences say what the papers report.
microcephaly (3 papers, 2019 to 2023). A congenital or acquired developmental disorder in which the circumference of the head is smaller than normal for the person's age and sex. "Mutations in the NUP133 gene were identified in the Galloway–Mowat syndrome 8, which is a rare severe renal–neurological disease characterized by early-onset nephrotic syndrome associated with microcephaly." (PMID 31878213, 2019). "Galloway-Mowat syndrome (GAMOS) is a group of rare hereditary diseases by the combination of early onset steroid-resistant nephrotic syndrome (SRNS) and microcephaly with brain anomalies caused by WDR73, LAGE3, OSGEP, TP53RK, TPRKB, GON7, WDR4 or NUP133 mutations." (PMID 36755238, 2023). "Zebrafish knock-out (KO) models showed microcephaly with fewer neuronal cells, which was rescued by wild-type but not mutant NUP133." (PMID 31878213, 2019).
Galloway-Mowat syndrome (2 papers, 2022 to 2023). Galloway syndrome is characterized by the association of nephrotic syndrome and central nervous system anomalies. "Notably, the autosomal recessive syndrome caused by SMPD4 loss shares several overlapping features with the Galloway –Mowat syndrome (GAMOS), which is associated with mutations in components of the Nup107-160 nuclear pore sub-complex (e.g., Nup133 and Nup107)." (PMID 35159279, 2022).
nephrotic syndrome (2 papers, 2019 to 2025). A collection of symptoms that include severe edema, proteinuria, and hypoalbuminemia; it is indicative of renal dysfunction. "In particular, previous genetic studies of patients with nephrotic syndrome identified mutations in Nup107 that impaired the expression or the localization of its direct partner at nuclear pores, Nup133." (PMID 30894603, 2019). "On the other hand, nup133 downregulation results in proteinuria and moderate foot process effacement, mimicking some of the abnormalities typically featured by patients with nephrotic syndrome." (PMID 30894603, 2019). "We report here that limited knockdown of zebrafish nup133, while not impairing early stages of kidney development, leads to glomerular abnormality that mimic nephrotic syndrome." (PMID 30894603, 2019).
viral infection (2 papers, 2018 to 2022). "Up-regulated differentially expressed genes (DEGs) indicated a clear relationship with the innate immune response against viral infection, including genes coding PRRs (LPG2 or DHX58) and IFN-stimulated genes (ISG15, Mx, STAT1, HERC5, IFI44, IFIT-1, NUP133, TRIM21)." (PMID 35215144, 2022). "Regarding upregulated DEGs, a clear relationship with the innate immune response against viral infection was observed, being unigenes detected those coding pattern recognition receptors (PRRs) (DHX58), and IFN-stimulated genes (ISG15, Mx, STAT1, HERC5, IFI44, IFIT-1, NUP133, and TRIM21)." (PMID 30065724, 2018).
breast carcinoma (1 paper, 2007). "Similarly, the presence of ABCB10 and NUP133, and candidate tumor suppressors LRRFIP1 and RNU3IP2 in the RB1-related cluster, further support their functional association in breast cancer." (PMID 17280605, 2007).
ciliopathy (1 paper, 2019). A genetic disorder of the cellular cilia or the cilia anchoring structures, the basal bodies, or of ciliary function. "Because the appearance of kidney cysts in zebrafish can also be caused by inactivation of several ciliopathy genes (reviewed in57,58), the observation of a mild Left-Right patterning defect in nup133 morphants was noteworthy." (PMID 30894603, 2019).
cyst (1 paper, 2019). A sac-like closed membranous structure that may be empty or contain fluid or amorphous material. "As previously proposed for other mutants), the pronephric cyst phenotype observed in the nup133 morphants might thus be primarily caused by alterations of the glomerular filtration barrier and the subsequent inability to osmoregulate, rather than the indirect consequence of cilia defect." (PMID 30894603, 2019).
heart failure (1 paper, 2025). Inability of the heart to pump blood at an adequate rate to meet tissue metabolic requirements. "We hypothesize that the downregulation of NUP133 may weaken the stability of the nuclear pore complex, indirectly promoting the occurrence and development of heart failure." (PMID 41477636, 2025).
Kidney Cyst (1 paper, 2019). Abnormal fluid filled sac within the kidney, either acquired or congenital. "Using a morpholino-mediated gene knockdown, we show that partial depletion of Nup133 in zebrafish larvae leads to the formation of kidney cysts, a phenotype that can be rescued by co-injection of wild type mRNA." (PMID 30894603, 2019). "In nup133 knockdown larvae with kidney cysts, however, irregularly-shaped processes covering the GMB were frequently observed, although typical foot processes were still present in some regions." (PMID 30894603, 2019). "We therefore stained cryosections of 3 dpf Tg(wt1b:EGFP) embryos either treated with control MO or treated with nup133 MO and featuring detectable kidney cysts." (PMID 30894603, 2019). "However, the BSA filtration defects observed in the nup133 morphants are consistent with the presence of kidney cysts (a phenotype that we could successfully rescue with injections of mRNA)." (PMID 30894603, 2019). "This indicates that the appearance of kidney cysts upon partial nup133 knockdown is not correlated with a Left-Right patterning defect and may therefore not result from a primary defect in cilia assembly or function (see discussion)." (PMID 30894603, 2019).
myeloma (1 paper, 2018). "Further studies including knockdown and overexpression of NUP133 in myeloma cells will be required to clarify the role of NUP133 in MM." (PMID 29861858, 2018).
infection (3 papers, 2014 to 2024). The state of being infected such as from the introduction of a foreign agent such as serum, vaccine, antigenic substance or organism. "Mutants defective for either of the common symbiosis genes SYMRK, CASTOR, POLLUX, NENA, NUP85, or NUP133 produce very similar phenotypes in symbiosis, in that they abort infection at the epidermis and are impaired in calcium-spiking, which placed them at the same hierarchical level." (PMID 25422918, 2014). "We observed that NUP98 protein levels were decreased both in SupT1 and HEK293T cell types upon HIV-1 NL4.3 infection by 4.7- and 1.5-fold, respectively (respectively), whereas the protein levels of other NUPs such as NUP62, NUP155, NUP133, NUP107, and NUP85 remained unaffected." (PMID 38449868, 2024). "Furthermore, unlike during infection, we observed downregulation of the protein levels of NUP62 and NUP85 by 1.2- and 2.1-fold, respectively, whereas NUP133 was upregulated by 1.5-fold." (PMID 38449868, 2024).
cancer (1 paper, 2020). A tumor composed of atypical neoplastic, often pleomorphic cells that invade other tissues. "The involvement of Nup133 in mediating such a response has broad implications because in humans, Nup133 is a constitutive cellular protein expressed in a lot of different cell types including a number of cancers." (PMID 32844334, 2020).
NUP133 also shares sentences with these, for which no sentence is quoted: cardiac diseases (1 paper); HIV-1 infection (1); kidney (1); multiple myeloma (1); situs inversus (1); steroid-resistant nephrotic syndrome (1).